PCBP2 (poly(rC) binding protein 2)
Diseases named in the same sentence as PCBP2 in open-access papers (continued):
Sharing a sentence is not in itself a finding about the gene and the disease.
gastric cancer (continued). "In gastric cancer cells HGC‐27 and MKN‐45, shRNA‐mediated PCBP2 depletion dramatically decreased cell viability as evaluated using a total cell number assay, cell colony formation assay and flow cytometry." (PMID 29744291, 2018). "PCBP2 and CDK2 were positively correlated in gastric cancer tissues (Pearson's correlation coefficient: r = 0.1718, P = 0.029)." (PMID 29744291, 2018). "The expression level of PCBP2 was significantly higher in gastric cancer tissues compared to adjacent nontumorous gastric tissues." (PMID 29744291, 2018). "PCBP2 and CDK2 were positively correlated in gastric cancer tissues." (PMID 29744291, 2018). "In the 200 samples of human gastric tissues (containing 100 cancers and 100 adjacent nontumorous tissues), PCBP2 showed a dramatically higher expression in gastric cancer tissues compared to adjacent nontumorous gastric tissues (67.5% versus 40%, P < 0.001)." (PMID 29744291, 2018). "However, when PCBP2 was silenced, the proliferation capacity of HGC-27 cells was obviously reduced, suggesting that PCBP2 could be a potential target for gastric cancer treatment." (PMID 37814239, 2023).
liver cancer (6 papers, 2019 to 2024). An epithelial or non-epithelial malignant neoplasm that arises from the liver. "To test whether MSI1 and PCBP2 overexpression was sufficient to activate rod-specific exons, we transfected these proteins into HepG2 cells, a liver cancer cell line used by the ENCODE project." (PMID 31919425, 2020). "Here, we reveal that in liver cancer cells, PCBP2 facilitates the TRIB2-induced reduction in global K48-Ub levels by elevating the activity of PSMB5, one of the major components of the proteasome that contains active sites." (PMID 33414446, 2021). "In conclusion, we’ve established a model emerges in which TRIB2 cooperates with and stimulates PCBP2 to reduce the global K48-Ub level in liver cancer cells." (PMID 33414446, 2021). "Mechanistically, glutathione peroxidase 4 functioned as one of the terminal effectors of TRIB2 and PCBP2 to protect liver cancer cells from oxidative damage." (PMID 33414446, 2021). "We find that PTBP1 knockdown and MSI1 and PCBP2 overexpression are sufficient to activate many photoreceptor-specific exons in HepG2 liver cancer cells." (PMID 31919425, 2020). "Additionally, CCT3 can also function independently by interacting with YAP and TFCP2 in liver cancer, thereby preventing the PCBP2-induced ubiquitination of these proteins." (PMID 39210442, 2024). "The interaction and function between TRIB2 and PCBP2 was also investigated in liver cancer cells." (PMID 33414446, 2021). "A significant correlation between TRIB2 and PCBP2 was revealed in liver cancer specimens." (PMID 33414446, 2021). "Here, we tested whether the relationship among CCT3, YAP, TFCP2 and PCBP2 is functional in maintaining transformative phenotypes in liver cancer cells." (PMID 31501420, 2019). "Thus, TRIB2 and PCBP2 maintain liver cancer cells viability via GPX4 to protect them against OS." (PMID 33414446, 2021). "However, whether TRIB2 interacts with PCBP2 to regulate Ub levels and how this interaction influences the viability of liver cancer cells under OS remain unclear." (PMID 33414446, 2021). "Here, we uncovered another tumour suppressive role of PCBP2 to reduce the protein stability of YAP and TFCP2 in liver cancer." (PMID 31501420, 2019). "In addition, all of these effects were reversed by treatment with PCBP2, suggesting that PCBP2 and TRIB2 increase liver cancer cell viability." (PMID 33414446, 2021). "Of note, TRIB2 and PCBP2 were also important for maintaining the viability of lung cancer A549 cells via GPX4, indicating that these effects might not be restricted to liver cancer cells." (PMID 33414446, 2021).
cervical cancer (5 papers, 2021 to 2025). A primary or metastatic malignant neoplasm involving the cervix. "In the risk model, LINC02535 has been shown that can enhance the stability of the downstream gene RRM1 by combining PCBP2 in cervical cancer." (PMID 33869203, 2021). "In addition, Wen and colleagues used cervical cancer cells to find that PCBP2 interacts with long non-coding RNA to stabilize RRM1 mRNA and promote epithelial mesenchymal transition and proliferation of cancer cells." (PMID 37814239, 2023).
hepatocellular carcinoma (5 papers, 2019 to 2025). A malignant tumor that arises from hepatocytes. "HNF4A-AS1 suppressed hepatocellular carcinoma progression via enhancing PCBP2 degradation through ubiquitin and destabilizing ARG2 mRNA." (PMID 40641925, 2025). "CircCPSF6, which was upregulated in hepatocellular carcinoma specimens, competitively interacted with PCBP2 to inhibit its binding to YAP1 mRNA, thus attenuating PCBP2-mediated destabilization of YAP1." (PMID 35701841, 2022). "In a human hepatoma cell line, it was demonstrated that the nucleotide-binding domain of NLRX1 attenuates hepatitis C virus (HCV)-triggered RIG-I-MAVS signaling by recruiting poly(rC) binding protein 2 (PCBP2) to MAVS." (PMID 33525671, 2021).
oral cancer (5 papers, 2015 to 2025). "Another multi-omic Atlas of Oral cancer data (CancerSEA) further validated the increased transcripts of PCBP2 in malignant oral epithelial cells, which was observed consistently in tumor cells across all 15 oral cancer patients examined." (PMID 39816681, 2025). "An earlier report described that PCBP2 was downregulated considerably in oral cancers and that PCBP2 overexpression induced apoptosis." (PMID 26196957, 2015). "In the oral cancers, hsa-miR-21 was found to be up-regulated while its target genes PCBP1 and PCBP2 were found to be down-regulated." (PMID 26064958, 2015).
prostate carcinoma (5 papers, 2023 to 2026). A carcinoma that arises from epithelial cells of the prostate gland. "At the mRNA level, PCBP2 expression is consistently elevated across all representative prostate cancer stages and cell line models, highlighting its potential significance in the immune regulation of PCa." (PMID 40051782, 2025). "While the cGAS-STING pathway has been well studied in tumor immunity, our findings provide novel insights into how PCBP2 specifically suppresses this pathway in prostate cancer, leading to immune evasion." (PMID 40051782, 2025). "Due to its high expression level in our cell lines, its upregulation in aggressive prostate cancers, and its ability to regulate other human UTRs, we focused our analyses on PCBP2." (PMID 38554103, 2024). "Curcusone C is a potential compound with anti-prostate cancer activity, and this effect occurs by targeting the PCBP2 protein, which in turn may affect the TGF/Smad signaling pathway and Bax/Bcl-2 balance." (PMID 37814239, 2023). "Similarly, our findings suggest that PCBP2 may suppress the cGAS-STING pathway in prostate cancer, potentially leading to PD-L1-mediated immune evasion." (PMID 40051782, 2025). "In conclusion, this study demonstrated that Curcusone C can target PCBP2 protein, thereby affecting TGF/Smad signaling pathway and Bax/Bcl-2 balance, and ultimately exert anti-prostate cancer activity." (PMID 37814239, 2023). "Our results indicated that Curcusone C can inhibit the proliferation and metastasis in prostate cancer cells through activating the expression of FHL3 and repressing PCBP2 through suppressing TGF/Smad signaling pathway, and the result was similar to studies of Mao and colleagues." (PMID 37814239, 2023).
glioblastoma (3 papers, 2019 to 2021). The most malignant astrocytic tumor (WHO grade IV). "PCBP2 expression was associated with poor prognosis in glioblastoma, and its overexpression increased colony formation and invasion capability." (PMID 32134197, 2020). "As a result, it will be necessary to validate the prognostic performance of IGF1R and PCBP2 in a larger independent cohort of glioblastoma." (PMID 32153627, 2019).
lung carcinoma (3 papers, 2021 to 2023). "In lung A549 adenocarcinoma cell lines and LUAD, PCBP2 was shown to bind to 5′ poly-C motif of MYMLR, a long non-coding RNA, regulating the transcription of MYC proto-oncogene; however, whether PCBP2 also regulates NT5E expression in lung cancer awaits further investigation." (PMID 33430239, 2021).
pancreatic cancer (3 papers, 2021 to 2025). "We also investigated the penetration of small molecules in stroma-rich pancreatic cancer spheroids after the treatment with the PCBP2 siRNA nanocomplex." (PMID 33500719, 2021). "The anti-tumor activity of the PCBP2 siRNA nanocomplex and its combination with gemcitabine was evaluated in an orthotopic stroma-rich pancreatic cancer mouse model." (PMID 33500719, 2021). "Overall, our data strongly support the hypothesis that a combination treatment with the CCP/PCBP2 siRNA nanocomplex and chemotherapy using gemcitabine should be considered a promising strategy for pancreatic cancer therapy due to its beneficial modulation of the fibrotic stroma." (PMID 33500719, 2021). "Circ_0005397 in pancreatic cancer, which activates PCBP2 expression through KAT6A-mediated H3K9 acetylation at the PCBP2 promoter, leading to enhanced GSH synthesis, GPX4 activation, and consequent chemoresistance." (PMID 40403492, 2025). "PCBP2, another member of the hnRNPE family, shares highly homology with PCBP1 in sequence and structure, but it was not correlated with prognosis in pancreatic cancer." (PMID 39170746, 2024).
asthma (2 papers, 2016 to 2023). "Similar to sarcoidosis, we observed several RBPs (AUF1, TIA, NCL and addition TIAR and PCBP2) to be decreased in our patients with IIPs, but not in our patients with airway obstructive pathologies (COPD and asthma) when comparing to healthy controls." (PMID 27575817, 2016).
colorectal cancer (2 papers, 2020 to 2025). A primary or metastatic malignant neoplasm that affects the colon or rectum. "The analysis of overall survival in colorectal cancer patient samples revealed that patients with high levels of GPX4, PCBP1, and PCBP2 had significantly worse overall survival." (PMID 40619432, 2025). "In colorectal cancer, ST8SIA6-AS1 served as a sponge of miR-5195 and elevated PCBP2, promoting tumor cell proliferation, migration, and invasion." (PMID 33363573, 2020). "Furthermore, PCBP1, PCBP2, and GPX4 synergistically promoted ferroptosis in colorectal cancer cells." (PMID 40619432, 2025).
melanoma (2 papers, 2022 to 2025). A malignant, usually aggressive tumor composed of atypical, neoplastic melanocytes. "A compelling mechanism of tumor suppression has been revealed, wherein miR‐5195‐3p was shown to inhibit melanoma cell proliferation and migration through direct downregulation of PCBP2, a known activator of the PI3K/AKT." (PMID 40740483, 2025). "Significantly reduced miR‐5195‐3p levels and elevated PCBP2 expression were detected in melanoma tissues, with a clear inverse correlation between the two." (PMID 40740483, 2025).
pancreatic ductal adenocarcinoma (2 papers, 2019 to 2022). An infiltrating adenocarcinoma that arises from the epithelial cells of the pancreas. "For example, PCBP2 expression was up-regulated in pancreatic ductal adenocarcinoma (PDAC) and was correlated with advanced PDAC stages as well as poor diagnosis." (PMID 31827399, 2019).
poliovirus infection (2 papers, 2011 to 2012). An disease or disorder caused by infection with Enterovirus C. "PCBP2 is also cleaved by viral-encoded proteases during a poliovirus infection, and this cleavage may help regulate the relative amounts of viral translation and replication." (PMID 22438951, 2012). "Since SRp20 co-localizes with PCBP2 and assists in ribosome recruitment during poliovirus infections, the possibility of PCBP2 co-factors for mediating viral RNA stability is plausible." (PMID 22438951, 2012). "Our imaging data of the co-localization of PCBP2 and SRp20 corroborates our previous in vitro interaction data using recombinant proteins and GST pull down assays, and illustrates the close proximity of PCBP2 and SRp20 in the cytoplasm of intact cells during poliovirus infection." (PMID 21779168, 2011). "Overall these studies have provided new evidence for the importance of PCBP2-SRp20 interaction in intact cells during poliovirus infection and suggest a model by which PCBP2, bound to the viral RNA, interacts with SRp20 and functions to recruit the translation initiation complex to the viral RNA." (PMID 21779168, 2011). "Thus, SRp20 and PCBP2 can be visualized in very close proximity to each other in the cytoplasm of intact cells during poliovirus infection." (PMID 21779168, 2011). "Finally, we generated a mutated version of SRp20 lacking the RNA recognition motif (SRp20ΔRRM) and found that this protein is localized similar to the full length SRp20, and also partially co-localizes with PCBP2 during poliovirus infection." (PMID 21779168, 2011). "To test this we carried out immunofluorescence experiments using a PCBP2 monoclonal antibody to investigate whether SRp20ΔRRM co-localized with PCBP2 during poliovirus infection." (PMID 21779168, 2011). "We hypothesized that an SRp20 protein lacking one of its functional domains would act as a dominant-negative protein when overexpressed in cells during poliovirus infection, effectively sequestering PCBP2 from functional viral translation complexes." (PMID 21779168, 2011).
acute myeloid leukemia (1 paper, 2022). Acute myeloid leukemia (AML) is a group of neoplasms arising from precursor cells committed to the myeloid cell-line differentiation. "In K562, an acute myeloid leukemia cell line, the knockdown of PCBP1 or PCBP2 alone did not affect cell growth." (PMID 36452487, 2022).
adrenocortical carcinoma (1 paper, 2022). "Moreover, PCBP2 is one of the ferroptosis risk signature genes and can predict the prognosis of adrenocortical carcinoma in combination with the other five ferroptosis risk signature genes." (PMID 35345408, 2022).
atherosclerosis (1 paper, 2025). A disease characterized by the build-up of fatty material and calcium deposition in the arterial wall resulting in partial or complete occlusion of the arterial lumen. "We also demonstrate how iron, as an environmental factor, interacts with PCBP2/rs1333046 to induce atherosclerosis‐associated cellular senescence." (PMID 41216990, 2025). "PCBP2 activates p16INK4a via the functional SNP rs1333046 on the atherosclerosis‐associated CDKN2A/B locus." (PMID 41216990, 2025). "Collectively, in this report, we demonstrate a new mechanism underlying the contribution of PCBP2/rs1333046 to atherosclerosis‐associated cellular senescence by modulating the p16INK4a and CD40‐mediated SASP gene expression." (PMID 41216990, 2025). "Thus, our studies suggest that iron could be a potential environmental factor regulating atherosclerosis‐associated cellular senescence, and this is achieved by modulating PCBP2‐dependent p16INK4a and CD40 expression." (PMID 41216990, 2025). "However, to fully understand the role that iron and PCBP2 play in regulating cellular senescence and atherosclerosis, a comprehensive in vivo functional study would be warranted." (PMID 41216990, 2025).
bladder urothelial carcinoma (1 paper, 2024). "In bladder urothelial carcinoma, MAFG-AS1 promotes deubiquitination of PCBP2 by binding to poly(rC)-binding protein 2 (PCBP2), thereby stabilizing PCBP2." (PMID 39210921, 2024).
breast invasive carcinoma (1 paper, 2019). "The interactive network shows that SNAPC5, PCBP2 and GNA13 are connected to other frequently altered genes from the TCGA breast invasive carcinoma dataset, which are also selected by other competing methods." (PMID 31534156, 2019).
cognitive decline (1 paper, 2025). "We then identify a small molecule CN-0928 that inhibits the condensates by reducing PCBP2 protein level and mitigates AD pathology and cognitive decline, in which CN-0928 binding to a target protein integrator complex subunit 1 (INTS1) allows to regulate PCBP2 expression." (PMID 41298370, 2025).
colon cancer (1 paper, 2025). "Additionally, we investigated the protein expression of PCBP1, PCBP2 and GPX4 in colon cancer patients via immunofluorescence staining." (PMID 40619432, 2025).
enterovirus infections (1 paper, 2023). "In addition to PCBP2 and GARS, there are many other ITAFs such as La, SRp20, and upstream of N-Ras (unr) that have been implicated in the initiation of Type 1 IRES-mediated translation initiation during other enterovirus infections." (PMID 38257775, 2023).
head and neck squamous cell carcinoma (1 paper, 2025). A squamous cell carcinoma that arises from any of the following anatomic sites: lip and oral cavity, nasal cavity, paranasal sinuses, pharynx, larynx, and salivary glands. "Moreover, the mRNA levels of EGFR and PCBP2 showed a positive correlation across different types of tumors, including head and neck squamous cell carcinoma (HNSCC)." (PMID 39816681, 2025).
HELLP syndrome (1 paper, 2021). A life-threatening condition that can potentially complicate pregnancy. "PCBP2 appears to be a paramount regulator of these differentiation mechanisms, where its disturbed binding to LINC-HELLP could contribute to dysfunctional placental development as seen in the HELLP syndrome." (PMID 34095140, 2021). "To conclude, in this study we show that PCBP2, through mRNA splicing, might be a paramount regulator of extravillous trophoblast EMT differentiation, where its disturbed binding to LINC-HELLP could contribute to dysfunctional placental development as seen in the HELLP syndrome." (PMID 34095140, 2021).
hepatitis C (1 paper, 2011). "Identification of the host factors that can predict sustained virological response (SVR) will undoubtedly improve the treatment of hepatitis C. We have found that PCBP2 plays an important role in influencing anti-HCV IFN-α." (PMID 22022391, 2011).
Hyperglycemia (1 paper, 2024). An increased concentration of glucose in the blood. "It is also interesting to note that PCBP2 decreases in islets from organ donors with T2D despite the hyperglycemia commonly experienced by these individuals." (PMID 38950317, 2024).
Insulin resistance (1 paper, 2024). Increased resistance towards insulin, that is, diminished effectiveness of insulin in reducing blood glucose levels. "PCBP2 overcomes palmitate-induced insulin resistance in HepG2 cells via inhibition of HIF1a and STAT378 but, in more advanced disease, PCBP2 promotes collagen production and liver fibrosis." (PMID 38291075, 2024).
liver fibrosis (1 paper, 2023). "This peptide-based nanocomplex provides a promising platform to effectively deliver Pcbp2 siRNA to activated HSCs for the treatment of liver fibrosis." (PMID 36979383, 2023).
malignant glioma (1 paper, 2016). A grade III or grade IV glioma arising from the central nervous system. "The RNA-binding protein PCBP2, an oncogenic protein in human malignant gliomas, is an essential regulator of mRNA and miRNA biogenesis, stability and activity." (PMID 26761212, 2016). "Our results also provide evidence supporting a model in which high-grade malignant gliomas, with increased PCBP2 levels, bind the ARHGDIA-3′UTR as well as miR-151-5p/miR-16, thereby inducing a conformational change in the ARHGDIA-3′UTR." (PMID 26761212, 2016). "Because the protein levels of ARHGDIA and PCBP2 were negatively correlated, combined ARHGDIA and PCBP2 levels may be considered as potential clinical diagnosis biomarkers or may be predictive of outcomes of malignant glioma patients after surgery." (PMID 26761212, 2016).
oral mucositis (1 paper, 2025). Inflammation of the mucous membranes of any of the structures in the mouth. "As the only exception, three putative autoantibodies were significantly higher in “mucosal toxicity” compared with “no toxicity” (PCBP2, COL6A1, SEMG1), referring to patients developing oral mucositis." (PMID 40449958, 2025).